JAK2 (Janus kinase 2)
Diseases named in the same sentence as JAK2 in open-access papers (continued):
Sharing a sentence is not in itself a finding about the gene and the disease.
acute pancreatitis (16 papers, 2017 to 2025). An acute inflammatory process that leads to necrosis of the pancreatic parenchyma. "In contrast, the renoprotective effect of curcumin in AKI caused by lipopolysaccharide (LPS) or severe acute pancreatitis may be associated with inflammation reduction mediated by suppression of JAK2/STAT3 signaling pathway." (PMID 33928100, 2021). "In a rat model of liver injury associated with severe acute pancreatitis, the inhibitor AG490 of JAK2 effectively reduced the serum levels of TNF, IL-6, and IL-18 by blocking excessive JAK2 and STAT3 activation." (PMID 38543164, 2024). "What is more, one previous study evidenced that JAK2/STAT3 signaling pathway played a central role in the advancement of acute pancreatitis." (PMID 35042436, 2022). "In view of this, the role of JAK2/STAT3 signaling pathway in cerulein-induced acute pancreatitis was important to explore." (PMID 35042436, 2022). "Studies on severe acute pancreatitis (SAP) in rats have found that JAK2 and STAT3 protein expression levels were significantly increased following induction of SAP." (PMID 35590365, 2022). "In rats with severe acute pancreatitis, curcumin was protective against acute renal injury by suppressing the JAK2/STAT3 pathway." (PMID 34434118, 2021). "Consistent with previous reports, our study also showed that the expression of NOX1, p22phox, p47phox, and p67phox NOX subunits increased by Jak2 activation in caerulein-induced acute pancreatitis, whereas this increase was attenuated by dunnione treatment." (PMID 30584237, 2018). "In view of this, we wondered whether FXYD5 downregulation could inhibit the inflammatory response in acute pancreatitis via regulating JAK2/STAT3 pathway." (PMID 35042436, 2022). "Moreover, other JAK/STAT family members, such as JAK2/STAT3 pathway, mediated adhesion molecule expression in a rat model of severe acute pancreatitis-associated lung injury and in endothelial cells." (PMID 34638942, 2021). "Since oxidative stress is involved in the pathogenesis of acute pancreatitis, DHA may prevent and/or inhibit the development of acute pancreatitis by suppressing the inflammatory signaling pathways, such as JAK 2/STAT 3, in the pancreatic tissues." (PMID 29068376, 2017). "Although a previous study sporadically showed that DCQD could regulate inflammatory cytokines and intestine injury in rats with severe acute pancreatitis via JAK2/STAT3 signaling pathway, the potential mechanism of DCQD participating in AP through JAK2/STAT3 is not clear." (PMID 33927777, 2021). "SAP contributes to hepatocyte injury during acute pancreatitis, and SAP-induced hepatocellular injury is consistent with the previous reports; the JAK2/STAT3 signaling pathway plays an important role on liver injury associated with SAP in the rat model." (PMID 34368363, 2021). "In severe acute pancreatitis induced acute lung injury, stellate ganglion block promoted the expression of SOCS5, inhibited the expression of miR-155-5p, and inhibited the activation of JAK2/STAT3 pathway." (PMID 38267898, 2024).
breast tumors (16 papers, 2014 to 2026). "We demonstrated that both LepR mRNA and FGFR1 mRNA were both positively associated with Jak2 mRNA in primary breast tumors." (PMID 33019728, 2020). "However a case control study of 223 breast tumors reported an association between increased JAK2 mRNA levels and favorable prognosis, and a strong correlation between JAK2 mRNA levels with the presence of tumor-infiltrating lymphocytes (TILs)." (PMID 26317899, 2015). "Evidence supports that BCSCs with the CD44+/CD24– phenotype are regulated by the Janus Kinase 2 (JAK2)/STAT3 pathway when compared to other breast tumor cells." (PMID 30542507, 2018). "This prediction is of particular interest because the JAK2 inhibitor Fedratinib was found to be synergistic with chemotherapy for breast tumor-initiating cells in autochthonous genetically engineered murine models." (PMID 28418910, 2017). "Preclinically, it was observed by injection of MMTV-Wnt-1 tumor cells into mammary fat pads of mice that inhibition of EPO-induced JAK2 activation by Fedratinib was synergistic with chemotherapy for breast tumor-initiating cells." (PMID 27494133, 2016). "Janus kinase inhibitors and monoclonal anti-IL6 receptor antibodies significantly decrease ALDH expression, colony, and mammosphere formation, suggesting possible use of pharmacological inhibitors of the IL-6/JAK2/STAT3 pathway in breast tumors with elevated POU1F1 levels." (PMID 41857068, 2026). "Ptpro deficiency was correlated with JAK2/YAP activation in both PyMT and human breast tumours." (PMID 40016288, 2025). "Significantly elevated expression of JAK2 in the non-epithelial compartment of breast tumors has been associated with a better prognosis and decreased risk of recurrence." (PMID 26317899, 2015). "Recent data have shown that the JAK2/STAT3 pathway is preferentially activated in CD44 + CD24- breast CSCs through the excessive production of IL6 and promotes CSC growth in breast tumors." (PMID 31511084, 2019). "However, it has been proved that Fe not only works fundamentally in many pathophysiological functions but also participates in the occurrence of breast tumors by interfering with signalings, such as VEGF, ROS, MAPK, and IL-6/JAK2/STAT3 signaling in animal models." (PMID 35782923, 2022). "Studies have shown that JAK2 genomic amplification and increased expression occur specifically in TNBC, but not ER+ and HER2+ breast tumors, correlating with poor clinical outcomes such as progression-free survival and overall survival." (PMID 40649917, 2025).
endometrial cancer (16 papers, 2013 to 2024). Primary or metastatic malignant neoplasm involving the endometrium (mucous membrane that lines the endometrial cavity). "This is first study to show that metformin targets pSTAT3 by degrading the protein and suppresses the upstream regulator JAK2 as well as the positive feedback regulator pNF-κB proteins in type 1 endometrial cancer cells." (PMID 28114390, 2017). "miR-204-5p has been shown to suppress the growth, migration and invasion of endometrial carcinomas by binding to TrkB mRNA and interfering with JAK2 and STAT3 phosphorylation." (PMID 28621736, 2017). "Furthermore, autocrine hGH-induced proliferative and anti-apoptotic effects have been shown to be mediated by the JAK2/STAT3 signaling pathway in endometrial carcinoma." (PMID 28617312, 2017). "Here, we show that STIP1 stabilizes JAK2 protein in ovarian and endometrial cancer cells." (PMID 27409672, 2016). "Moreover, inhibition of STAT3 by small interference RNA (siRNA) elevated the miR-204-5p expression in IshikawaTrkB and HEC-1B cells (P < 0.05), indicating that, indeed, TrkB activates the JAK2/STAT3 pathway in endometrial cancer cells." (PMID 24321270, 2013). "Recent evidence has shown that ADCS provoke an increase in IL6 levels, which induces the phosphorylation of JAK2/STAT316, resulting in proliferation, invasion and tumor growth in prostate and endometrial cancers." (PMID 32848147, 2020). "Next, we examined the variances in the mRNA and protein expression of JAK2 and STAT3 in the Ishikawa endometrial cancer cells treated with 5 μM of cisplatin and 10–40 ng/mL of leptin." (PMID 32531934, 2020). "The results showed that cisplatin reduces the transcriptional activity of selected genes, while leptin promoted the expression of mRNA JAK2 and STAT3 in endometrial cancer cells (p < 0.05)." (PMID 32531934, 2020). "The obtained results showed that leptin siRNA inhibited the expression of JAK2 and STAT3 proteins both in the Ishikawa culture untreated with cisplatin (0 h) and the endometrial cancer culture incubated with cisplatin for 12, 24 and 48 h." (PMID 32531934, 2020). "The downstream signaling of JAK2/STAT3 pathway activates several mechanisms responsible for the progression of ovarian and endometrial carcinomas." (PMID 28686225, 2017). "In the present study, in endometrial cancer cells, upregulation of LSR by metformin via MAPK and upregulation of LSR via MAPK, PI3K and JAK2/STAT were observed." (PMID 27036040, 2016). "In addition, in endometrial cancer cells, downregulation of LSR by leptin via PI3K and JAK2/STAT and upregulation of LSR by adiponectin via MAPK and JAK2/STAT were observed." (PMID 27036040, 2016). "Thus, unlike our previous finding in endometrial cancer where JAK1 frameshift was the predominant mechanism of the IFNγ-IRF1 pathway genetic defects, JAK2 gene deletion was the predominant mechanism of the IFNγ-IRF1 pathway genetic defects in NSCLC." (PMID 28977839, 2017).
Hepatic steatosis (16 papers, 2012 to 2026). Steatosis is a term used to denote lipid accumulation within hepatocytes. "Hepatic steatosis observed in both JAK2-deficient lines was not only a result of ectopic FA uptake but also resulted from enhanced expression of key enzymes involved in de novo lipogenesis." (PMID 27713471, 2016). "Furthermore, elevated leptin levels have been linked to the worsening of hepatic steatosis, as leptin activates the JAK2/STAT3 pathway, increasing the expression of the suppressor of SOCS3, which contributes to hepatic lipid accumulation." (PMID 40862455, 2025). "Here, we addressed the impact of hepatic JAK2 deficiency on the progression of hepatic steatosis." (PMID 27713471, 2016). "The development of hepatic steatosis has been observed in mice with liver-specific deletion of the GH receptor (GHR), liver-specific JAK2-deficient mice, or STAT5-deficient mice." (PMID 38836220, 2024). "Treatment of fructose-induced hepatic steatosis mice with 150 mg kg−1 body weight of kefir peptides significantly inhibited the expression of the leptin receptor (OB-R) and increased the expression of p-JAK2, STAT3 and p-STAT3." (PMID 27941940, 2016). "RECENT FINDINGS: Experimental evidence supports a direct effect of GH on hepatocytes predominantly through the Janus kinase 2 (JAK2)–signal transducer and activator of transcription 5 (STAT5) pathway, which reduces hepatic steatosis." (PMID 41708551, 2026). "This increased JAK2 ubiquitination suppresses the JAK2–STAT5–PPARγ signalling pathway and reduces hepatic steatosis." (PMID 39471843, 2024). "It has been identified that circSCD1 stimulates protein expression of JAK2 and STAT5 and ultimately affects the pathogenesis of NAFLD by promoting hepatic steatosis via the JAK2/STAT5 pathway." (PMID 36407314, 2022). "Genetic deletion of the tyrosine kinase JAK2 or the downstream transcription factor STAT5 in liver impairs growth hormone (GH) signalling and thereby promotes fatty liver disease." (PMID 27713471, 2016). "Various studies show that puerarin may regulate leptin signaling through the Janus kinase 2 (JAK2)/STAT3 pathway, thereby ameliorating hepatic steatosis." (PMID 37375652, 2023). "Furthermore, ANGPTL4 improved glucose tolerance and IR by downregulating insulin signaling pathway-associated genes, such as Akt, Janus kinase 2/signal transducer and activator of transcription-3 (JAK2/STAT3), but promoted diet-induced hepatic steatosis." (PMID 37180779, 2023). "In addition, basic research proposed that chemerin also ameliorated liver steatosis, lobular and portal inflammation in NASH mice by promoting autophagy and alleviating oxidative stress through JAK2/STAT3 phosphorylation." (PMID 37180779, 2023). "Aerobic exercise intervention (EM group) notably increased PRLR, p-JAK2, and p-STAT5 levels (P < 0.01), indicating that exercise may mitigate hepatic steatosis in NAFLD mice, likely through activation of the classical PRLR-mediated JAK2/STAT5 signaling pathway in liver." (PMID 40894210, 2025).
ischemia (16 papers, 2011 to 2025). A hypoperfusion of the BLOOD through an organ or tissue caused by a PATHOLOGIC CONSTRICTION or obstruction of its BLOOD VESSELS, or an absence of BLOOD CIRCULATION. "A previous study has shown that the JAK2/STAT3 pathway plays a vital role in hepatic ischemia/reperfusion injury." (PMID 40141803, 2025). "The serum levels of interleukin (IL)-17A and IL-21 were decreased, and the expression of JAK2/STAT3 proteins was inhibited in all RJQM treatment groups compared to the ischemia group." (PMID 36034959, 2022). "Its expression is rapidly induced by ischemia–reperfusion injury, promoting leukocyte adhesion to ECs via the Janus kinase 2 (JAK2)-signal transducer and activator of transcription 3 (STAT3) pathway by upregulating vascular cell adhesion molecule-1 (VCAM-1) expression." (PMID 40332339, 2025). "Our investigation demonstrated that JB inhibited the phosphorylation of JAK2 and STAT3, thereby blocking the JAK2/STAT3 signaling pathway, promoting M2 polarization of microglia, and alleviating ischemia–reperfusion injury." (PMID 41254929, 2025). "Within the CNS, the JAK2/STAT3 signaling pathway can be activated in response to stimulus conditions, such as ischemia, trauma, and radiation, and is involved in the regulation of apoptosis, inflammatory responses, vascular remodeling, oxidative stress, and cellular autophagy." (PMID 40406486, 2025). "The reperfusion injury signaling kinase (RISK) pathway including PI3K/Akt signaling cascade and the protective survivor activating factor enhancement (SAFE) pathway including JAK2/STAT3 signaling cascade are the most important pathways involved in eNOS activation and ischemia myocardial protection." (PMID 21912612, 2011). "Compared to the vehicle control, in rats treated with AG490, as a JAK2 phosphorylation inhibitor, in the sham group, JAK2 and STAT3 phosphorylation did not occur after ischemia; also, the infarct volume and apoptotic cells were significantly decreased, and neurological deficits were improved." (PMID 37786415, 2022). "Recently, BBR has been reported to inhibit the phosphorylation of JAK/STAT3 signaling without altering the total proteins of JAK2 and STAT3 to protect rat heart from ischemia/reperfusion injury, suggesting that JAK2 may not be the direct target of BBR." (PMID 32213189, 2020).
acute kidney injury (15 papers, 2013 to 2025). Sudden and sustained deterioration of the kidney function characterized by decreased glomerular filtration rate, increased serum creatinine or oliguria. "In a septic acute kidney injury mouse model, curcumin showed anti-inflammatory capacity and attenuation of apoptosis by JAK2/STAT3 and NF-κB signaling pathway inhibition, resulting in increased levels of Bcl-2 and decreased levels of Bax and caspase-3." (PMID 39203857, 2024). "Combining the most common mutations in cell signaling genes such as NRAS, CBL, and JAK2, the prevalence of these aberrations was 55% in CMML patients with renal failure as compared to 38% among patients with normal kidney function (p = 0.056)." (PMID 36282402, 2023). "According to reports, curcumin exhibits the attenuation of inflammation by modulating the NF-κB and JAK2/STAT3 signaling pathways in response to acute kidney injury." (PMID 37627579, 2023). "The ability of AG490 to inhibit JAK2 activity and suppress the activation of STATs 1 and 3 has rescued the kidneys from renal failure during IRI." (PMID 34948185, 2021). "Studies have shown that activation of the JAK/STAT signaling pathway contributes to the development of acute kidney injury; thus, we used the JAK2-specific antagonist AG490 as a positive control treatment of kidney injury." (PMID 32620154, 2020). "miR-155-5p enhances oxalate- and calcium-triggered kidney oxidative stress injury by repressing matrix gla protein (MGP) expression and aggravating both inflammation and apoptosis in acute kidney injury tissues via the Jak2/Stat3 pathway." (PMID 33457405, 2020). "This patient, having a 4-year history of JAK2-positive post-ET MF, developed persistent diarrheas and acute renal failure." (PMID 31781224, 2019). "Similarly, α7nAChR reduced the inflammatory response by modulating NF-κB (p65) and IL-6/JAK2/STAT3/SOCS3 signals in acute kidney injury (AKI) model." (PMID 37429998, 2024). "We present a nephrotic syndrome in PMF-related glomerulopathy, associated with EMH, without renal failure, in a patient under treatment for 2 years with JAK2 inhibitor ruxolitinib." (PMID 29350220, 2017). "In an acute kidney injury model, IL - six promotes ferroptosis by reducing glutathione (GSH) in renal tubular cells through the activation of the JAK2/STAT3 axis." (PMID 40371332, 2025). "Additionally, GAL reduced JAK/STAT3 expression in acute kidney injury (AKI) model through modulation of NF-κB (p65) and IL-6/JAK2/STAT3/SOCS3 signals via α7nAChR and in experimental asthma model, α7nAChR exerted promising effects by inhibiting NF-κB/STAT3/SOCS3 signaling." (PMID 37429998, 2024). "In murine acute kidney injury, QM56 decreased tubular cell apoptosis and kidney inflammation as measured by down-modulations of MCP-1 and Rantes mRNA expression, immune cell infiltration and activation of the JAK2-dependent inflammatory pathway." (PMID 23300960, 2013).
chronic lymphocytic leukemia (15 papers, 2014 to 2025). "While familial relative risks attributed to this variant are smaller (e.g., <3% for Chronic Lymphatic Leukemia (CLL)), the genotypic relative risks reported for JAK2-positive MPNs are among the highest described in genome-wide association studies." (PMID 41226376, 2025). "Other findings revealed that in B-cell chronic lymphocytic leukemia (B-CLL), JAK2 on the surface of B cells promoted cell adhesion and survival in bone marrow stromal niches by activating αLβ2 and α4β1 integrins, mediating B-cell-dependent adhesion and depression in secondary lymphoid-like organs." (PMID 37047140, 2023). "HES/Sjögrens, AOSD flare, HLH testing, chronic lymphocytic leukemia, morphea, FMF, bilateral hygroma, polyarthralgia, AOSD/FMF, Jak2+Cytosis, Jak2+ myeloproliferative syndrome, chemotherapy-induced fever, Castleman’s?" (PMID 37600813, 2023). "In addition, inhibition of JAK2 or BTK, downstream effectors of CXCL12, inhibits integrin activation and suppresses tumor cell adhesion, survival, and spread in B-cell chronic lymphocytic leukemia (B-CLL)." (PMID 37047140, 2023). "The JAK2/STAT3 in particular has a key role in conveying signals that elicit the transcription of pro-survival and anti-apoptotic genes, such as Mcl-1 and Bcl-2, both known to be over-expressed in chronic lymphocytic leukemia (CLL)." (PMID 31817171, 2019).
coronary heart disease (15 papers, 2012 to 2026). "The JAK2 V617F variant has previously been shown to be associated with vascular complications, including coronary artery disease, peripheral artery disease, and abdominal aortic aneurysms." (PMID 39062663, 2024). "A seminal study from 2017 identified an association between mutations in the DTA and JAK2 genes and coronary disease." (PMID 34068690, 2021). "This “clonal haematopoiesis of indeterminate potential” or CHIP is associated with a significantly elevated risk of coronary artery disease when the driving mutation is JAK2." (PMID 30574023, 2018). "Furthermore, the trial identified specific mutations in DNMT3A, TET2, ASXL1, and JAK2 as independent contributors to heightened coronary heart disease risk." (PMID 41458386, 2025). "Moreover, in a recent study, the presence of clonal haematopoiesis of undetermined significance in peripheral blood cells was associated with an increased risk of coronary heart disease, with the highest risk corresponding to the JAK2 p.V617F mutation." (PMID 33420222, 2021). "In support of the link between constitutive JAK2 activation and increased risk of vascular events, the rs3184504 SNP in the SH2B3 (LNK) gene was also associated with an increased risk of coronary heart disease." (PMID 34068690, 2021). "In a study that included subjects with coronary heart disease and controls, each major CHIP‐driving mutations, DNMT3A, TET2, ASXL1, and JAK2, was associated with an increased risk of coronary heart disease, but the hazard ratio was the lowest for the DNMT3A mutation." (PMID 36807865, 2023).